VDR (vitamin D receptor)
Diseases named in the same sentence as VDR in open-access papers (continued):
Sharing a sentence is not in itself a finding about the gene and the disease.
tumor (continued). "Mechanistically, calcitriol inhibits tumor growth by promoting apoptosis, suppressing angiogenesis, and modulating the tumor microenvironment through VDR-mediated gene regulation." (PMID 40218858, 2025). "Yet, targeting treatments for VDR in ATC remains limited because this highly differentiated tumor often loses expression of VDR and other differentiation markers." (PMID 40071065, 2025). "Factors such as tumor heterogeneity, differential VDR expression across tumor subtypes, and local tumor microenvironmental influences, including immune infiltration and stromal interactions, likely contribute to these variable outcomes." (PMID 41377467, 2025). "The expression of VDR in epithelial and stromal colon cells plays a crucial role in tumor progression." (PMID 41020251, 2025). "In this respect, it is one of the pioneering publications aiming to investigate the relationship between VDR expression in tumor cells in preoperative breast biopsy specimens and prognostic indicators." (PMID 40898467, 2025). "VDR knockdown significantly inhibited cell proliferation, tumor growth, and reduced gefitinib resistance, whereas VDR overexpression enhanced resistance." (PMID 40872626, 2025). "Low cytoplasmic VDR correlated with increased tumor staging (Cc = -0.422), positive lymph node status (Cc = -0.375), and higher stage groups (Cc= -0.438)." (PMID 38265102, 2024). "We conducted a bioinformatics analysis and found that the high expression of VDR in PAAD is associated with a poor prognosis and the presence of immune cells, particularly an increased infiltration of M2 macrophages in the tumor tissue." (PMID 38600588, 2024). "Cytoplasmic/membranous VDR expression was detected in tumor cells of 19 (54.3%) cases, and of these 37.1% showed low expression and 17.1% showed high expression." (PMID 38265102, 2024). "The Taq1 GG and Bsm1 TT VDR genotypes were associated with improved clinical outcome and the prognostic impact of the Fok1 AA VDR genotype was dependent on tumor size." (PMID 38351438, 2024). "Qu also inhibits tumor angiogenesis not only via the VEGF pathway but also by downregulating vitamin D receptor expression and alleviating hypoxia within the TME." (PMID 39712006, 2024). "Differences in cytoplasmic/membranous VDR expression were found in relation to tumor histology (p=0.018), tumor necrosis (p=0.022), and stage groups (p=0.001)." (PMID 38265102, 2024). "The tumor volume of overexpressing VDR was significantly larger than the control group, while flow analysis showed a higher number of M2/M1 macrophages infiltration than the control group." (PMID 38600588, 2024). "The anti-tumor properties of vitamin D and its analogs are mediated by vitamin D receptor (VDR) binding to vitamin D response elements in DNA and subsequent changes in gene expression." (PMID 38771847, 2024). "This further emphasizes the need for caution when considering the use of VitD activated VDR anti-tumor supplementation in clinical settings." (PMID 38600588, 2024). "In order to further confirm the suppressive role of VDR in tumor, VDR was overexpressed by adenovirus in K1 and BCPAP cells." (PMID 38639057, 2024). "This observational study aimed to determine the relationships between clinicopathological characteristics of female patients with BC after NAC and the expression of VDR (measured as IRS) in tumor cells and their microenvironment." (PMID 39411136, 2024). "Studies have found that signals from the 1,25(OH)2D3 receptor (VDR) and calcium-sensing receptor (CaSR) can inhibit tumor proliferation and metastasis, and promote tumor differentiation and apoptosis." (PMID 39687887, 2024). "Although nuclear VDR was predominant in patients’ tumor tissues, it showed only a significant statistical relationship with the AJCC stage groups (nuclear expression increased in more advanced tumors)." (PMID 38265102, 2024).
tumor (continued). "There were significant interactions between VDR and invasive tumor size (Pinteraction = 0.047), as well as mode of detection (Pinteraction = 0.049)." (PMID 38612962, 2024). "Our study revealed elevated expression of supernatant CCL20 in tumor cells, and the effect of overexpression of VDR tumors on macrophages disappeared after we blocked CCL20." (PMID 38600588, 2024). "Our study demonstrates for the first time that high VDR expression in PAAD cells promotes CCL20 transcription and release, inducing functional changes in tumor-associated macrophages." (PMID 38600588, 2024). "In a snapshot, the authors found that intestinal VDR helps keep the intestinal barrier structure and function and also acts as a tumor suppressor by regulating the JAK/STAT pathway in the intestine." (PMID 38318147, 2024). "We performed immunofluorescence staining of 19 cases of PAAD and paired paracancerous tissues and found that VDR expression was higher in tumor tissues." (PMID 38600588, 2024). "There were higher M2/M1 ratios in the 200 μm range of VDR-positive cells both in the tumor and stroma." (PMID 38600588, 2024). "This epigenetic silencing of VDR can impair its tumor-suppressive functions, including the regulation of gene expression and apoptosis." (PMID 38230221, 2024). "We confirmed that tumor tissues overexpressing VDR contained a higher ratio of M2/M1 macrophages in both the tumor and stroma." (PMID 38600588, 2024). "Our results indicated that VDR expression was positively correlated with neutrophils and dendritic cells and negatively correlated with tumor cell purity in CESC patients." (PMID 39268267, 2024). "Vitamin D and its receptor (VDR) have in some studies been shown to counteract tumor progression and enhance different treatments, which merits further investigation." (PMID 38351438, 2024). "VDR, as a transcription factor, is widely expressed in multiple tumor tissues and regulates the expression of a variety of downstream signaling molecules." (PMID 38639057, 2024). "The expression of VDR in tumor cells and their microenvironment is related to the clinicopathological characteristics of BC after NAC." (PMID 39411136, 2024). "The higher the number of NAC cycles, the larger the VDR-IRS of tumor cell cytoplasm compared to normal cells, and a similar, though weaker, effect was observed for nuclear VDR-IRS." (PMID 39411136, 2024). "VDR was expressed in the nucleus in adjacent non-tumor tissues, but mainly located in the cytoplasm and cell membrane and showed stronger staining in PTC tissues." (PMID 38639057, 2024). "Researchers widely believed that, activated VDR is a promising anti-tumor strategy with Vitamin D (VitD) serving as its activator." (PMID 38600588, 2024). "Conversely, in the Pan02 cell line with knockdown of VDR, the rate of tumor cell proliferation in vivo was partially restored following overexpression of CCL20." (PMID 38600588, 2024). "To investigate the relationship between intra-tumor VDR and M2 macrophages recruitment, we performed macrophages migration assay." (PMID 38600588, 2024). "VDR signaling pathway has a crucial role in several physiological activities, such as bone development, anti-inflammatory response, and anti-tumor activities." (PMID 38318147, 2024). "In tumor-derived endothelial cells, the transcription of one of the VDR target genes, 24-hydroxylase (CYP24A1) is upregulated and this promotes the metabolism of 25-D and 1,25-D." (PMID 38846332, 2024). "This discrepancy between studies can be explained by the different studied tumor types, different used VDR antibody clones, variable cut offs used for positivity, as well as polymorphisms in the VDR gene." (PMID 38265102, 2024). "Knockout of VDR increases carcinogen-induced mammary hyperplasia and tumor progression in the epidermis and lymphoid tissue in mice." (PMID 38639057, 2024). "We analyzed the expression of the VDR in relation to immune cell type and tumor cell purity in CESC." (PMID 39268267, 2024).
tumor (continued). "In this study, we showed that the expression of VDR in tumor cells and its microenvironment is related to various clinicopathological characteristics of BC (including those of well-known prognostic meaning) after NAC." (PMID 39411136, 2024). "We performed a 6-color mIHC staining on tissue microarray (TMA) samples to evaluate the tumor area and the densities of VDR overexpression cells, CCL20 overexpression cells, M2 macrophages and M1 macrophages." (PMID 38600588, 2024). "In patients with CESC, the VDR expression is positively correlated with neutrophils and dendritic cells and negatively correlated with tumor cell purity." (PMID 39268267, 2024). "The first evidence of vitamin D growth inhibitory effects in tumor cells was shown by Colston and colleagues by demonstrating a pivotal role of VDR in malignant melanoma." (PMID 39335182, 2024). "This is because when the VDR gene was deleted, a decrease in claudin-5 and an increase in tumor development were observed." (PMID 38318147, 2024). "Lentiviral VDR expression vector construction and transfection.Proliferation, migration, invasion, and spheroid colony formation assays.Tumor volume in xenografts.Immunohistochemestry (IHC)for tissue samples.Western blot for protein levels." (PMID 39683479, 2024). "The level of VDR protein was usually lower in tumour samples, while SIRT1 protein expression showed high variability between tumors and high cellular intratumor heterogeneity." (PMID 37530744, 2023). "The inhibition of VDR by its antagonist blocks PD-L1 expression, reduces the tumor burden in nude mice, and promotes anti-tumor immunity in acute myeloid leukemia, ovarian cancer, and pancreatic cancer." (PMID 38203175, 2023). "A possible reason for this phenomenon is that VDR becomes more sensitive to downregulation as the tumor progresses into a more advanced stage." (PMID 37960224, 2023). "Studies have shown that VD and VDR affect the stemness of CCSCs and that the acidic tumour microenvironment leads to a reduction in VDR expression and affects the stemness of CRC cells by regulating the expression of SOX2." (PMID 36846715, 2023). "To model CRCs patients with low VDR tumour level or with VD deficiency, we used an HCT 116-derived cell line stably depleted of VDR using shRNA (hereafter named ShVDR)." (PMID 37530744, 2023). "VDR expression can be used as a supplement to tumour node metastasis (TNM) staging of digestive system tumours." (PMID 37561808, 2023). "Recent research suggests that both the levels of the progenitor of calcitriol (25(OH)-vitamin D3; calcidiol), as well as VDR expression, correlate with tumor burden and/or progression of brain tumors." (PMID 37958423, 2023). "Activation of VDR by its ligand is involved in the inhibition of tumor cells proliferation, invasion, migration, and angiogenesis." (PMID 37153919, 2023). "Expression of VDR was shown to exhibit tumor-suppressing and anti-proliferative effects, promoting apoptosis and inhibiting angiogenesis." (PMID 37242266, 2023). "The potential relevance of the Akt- and mTOR pathways in VitD/VDR signaling is supported by reports in other tumor types." (PMID 36902107, 2023). "VDR expression highly correlated with the histological differentiation of the tumor, in contrast to the RXRα levels (n = 540, p = 0.0002 ***/p = 0.0056 **)." (PMID 36902107, 2023). "In order to correlate the VitD serum levels with VDR expression in the tumor tissues, peripheral blood samples were taken from the patients before or during surgery." (PMID 36902107, 2023). "First, by analyzing our cohort of n = 40 HNC patients compared to healthy controls (n = 40), we demonstrated that both the VitD serum levels and VDR expression correlate with clinical parameters such as histopathological tumor classification." (PMID 36902107, 2023).
tumor (continued). "In the pancreas, increased expression of VDR has been reported in PC cells and tumour tissue compared to normal tissue." (PMID 37509236, 2023). "An elegant series of studies found that the VDR signaling affect tumor development by the delicate interplay with E-cadherin and the Wnt signaling pathway." (PMID 36845724, 2023). "VDR signaling was shown to abrogate the pro-tumor effects of CAFs in pancreatic cancer by suppressing the secretion of exosomal miR-10a-5p." (PMID 37175993, 2023). "In order to closely approach the tumor situation in vivo, we next established HNC 3D tumor spheroids to investigate the effects of VitD/VDR targeting in an experimental setting, more closely mimicking the patients’ tumor microenvironments." (PMID 36902107, 2023). "In this study, FXR and VDR gene expression was upregulated in the colons of HF-fed mice with a reduced number of tumours." (PMID 36768196, 2023). "In a third cohort of AA and EA patients VDR cistrome genes were examined in which DEG analyses in tumor and contralateral normal material was available." (PMID 37082578, 2023). "By inhibiting Wnt/β-catenin signaling through the activation of VDR, calcitriol inhibits tumor proliferation and growth." (PMID 38269250, 2023). "The over-expression of VDR is described as an endogenous reaction to tumor progression correlated with a favorable prognosis." (PMID 37242266, 2023). "Thirteen days later, the tumour volume and weight from the VDR-overexpressing mice were significantly reduced compared with those of the controls (**P < 0.01)." (PMID 37046222, 2023). "Vitamin D analogues bind to VDR in tumour cells and activate downstream pathways to inhibit tumour growth." (PMID 37561808, 2023). "This study is the first to investigate the possible presence of VDR in pediatric tumor specimens, group entities based on the findings and to examine the role of these findings as a potential prognostic factor." (PMID 35884356, 2022). "1,25(OH)2D3 is known to inhibit NF-κB activation by forming VDR-p65 complex, increases the level of IκBα, or strengthens the interaction between VDR and IKKβ, thereby restraining inflammation and tumor growth." (PMID 36267284, 2022). "To further verify the tumor-suppressive effect of VDR in vitro tumorigenesis assays, we examined the tumor formation in WRO or K1 cell xenografts." (PMID 35099410, 2022). "Consistent with our in vitro data, the results showed that VDR remarkedly delayed DTC tumor growth in xenograft in SCID mice." (PMID 35099410, 2022). "The results showed that tumor volume and weight were increased significantly in the VDR knockdown group when compared with the control group." (PMID 35099410, 2022). "VDR functions as a master transcriptional regulator, where its activation suppresses tumor-supporting signaling pathways." (PMID 35345849, 2022). "As vitamin D is known to directly suppress tumour growth via the VDR, adequate vitamin D levels are of utmost importance for patients with bone metastases." (PMID 36362766, 2022). "To confirm the effect of VDR knockdown on DTC tumor growth, we examined the effects of overexpression of VDR in a xenograft experiment using SCID mice (n = 6 for each group)." (PMID 35099410, 2022). "VDR signalling is of obvious importance in tumour cells but also in inflammatory cells, immunocytes and angiocytes." (PMID 35445563, 2022). "Larger or deeper tumours are likely to be more advanced and thus, VDR signalling less likely to be intact." (PMID 35445563, 2022). "Co-culture of VDR-overexpressing tumor cells and a macrophage cell line demonstrated that overexpression of VDR alleviated the pro-metastatic effect of co-cultured macrophages on BC cells and abrogated the induction of EMT." (PMID 36294305, 2022). "Studies also revealed that VDR overexpression significantly reduced the sizes and numbers of tumor spheres formed by CRC stem cells." (PMID 35447933, 2022).
tumor (continued). "The combination of VDR agonists and hypomethylating agents can promote leukemic stem cell depletion and reduce tumor burden." (PMID 36211454, 2022). "The activated form of vitamin D, calcitriol, binds to VDR to promote cell differentiation and apoptosis and inhibit cellular proliferation, angiogenesis, and tumor cell invasion." (PMID 35982094, 2022). "In our study, the serum vitamin D level was higher in the group with a small tumor volume, which can be seen as a result of angiogenesis inhibition or cell cycle arrest through VDR." (PMID 35982094, 2022). "Using multiply imputed data on VDR status diminishes this selection bias to some extent since values on VDR status can be imputed on small tumors, taking tumor size into account." (PMID 36014861, 2022). "Our observation of the tumor samples of the sympathetic nervous system where VDR expression was observed in mature components, such as ganglion cells, is consistent with previous data in the literature." (PMID 35884356, 2022). "Combined with a model that promotes intestinal inflammation, the potential role of VDR as a tumor initiator was examined." (PMID 35662320, 2022). "We determined the percentages of the appearance of VDR-expressing tumor cells on TMA blocks and scored them." (PMID 35884356, 2022). "The Kaplan–Meieranalysis showed statistically greater survival prospects for the treatmentgroups.Immunohistochemistry (IHC) shows reduced VDR expression in a randomlyselected 5-treated SKOV-3 xenograft tumor invivo." (PMID 35404047, 2022). "Mechanism studies have found that signals from the 1, 25 (OH)2D3 receptor (VDR) and calcium-sensing receptor (CaSR) can inhibit tumor proliferation and metastasis and promote tumor differentiation and apoptosis." (PMID 36364831, 2022). "VDR mRNA expression was lower in ACC than in benign adrenocortical lesions and VDR immunostaining was evident in benign lesions while it appeared weak in tumor tissues." (PMID 36313775, 2022). "This study revealed a novel mechanism of anticancer action of vitamin D/VDR through maintenance of the right proportion of oncogenic to tumor-suppressing lncRNAs." (PMID 35328609, 2022). "Work is needed in assessing the integrity of tumour VDR signalling and the safety of vitamin D3 supplementation when defective." (PMID 35445563, 2022). "The H19 lncRNA was suggested to be involved in the maintenance of the right proportion of oncogenic to tumor-suppressing lncRNAs in a vitamin D3/VDR signaling-dependent manner." (PMID 35328609, 2022). "We found that the rate of VDR expression differed significantly between various tumor types (p < 0.0001)." (PMID 35884356, 2022). "The reported beneficial effect of vitamin D3 on tumour immunity would appear dependent on tumour cell VDR signalling." (PMID 35445563, 2022). "The tumor volume and the mean tumor weight were lower in mice xenografted with VDR overexpressed K1 cells compared to those xenografted with cells transfected with the vector control, indicating that VDR inhibits tumor growth." (PMID 35099410, 2022). "It has also been shown that the expression of VDR in myoma tissue is significantly lower than in the uterine muscle tissue at the tumor periphery." (PMID 36014877, 2022). "Several studies have shown the role of the alteration of VDR methylation in various neoplasms; the study of Mai Abdalla evaluated the methylation of the VDR promoter as a potential biomarker for the identification of HCC." (PMID 36012285, 2022). "One of the most widely used methods to study the presence and pattern of VDR protein expression in certain tumor tissues is immunohistochemistry." (PMID 35884356, 2022). "The active form of vitamin D then acts on vitamin D receptor (VDR), which is expressed not only in bone and intestine but also in bone marrow, brain, pancreas, prostate, tumor cells, and immune cells." (PMID 36259029, 2022).